STON2 (stonin 2)
Description:
Adapter protein involved in endocytic machinery. Involved in the synaptic vesicle recycling. May facilitate clathrin-coated vesicle uncoating.
Synonyms: STN2; STNB; STNB2
Tractability: PROTAC: UniProt records ubiquitination sites on it; ubiquitination databases record sites on it; its protein half-life has been measured.
Gene: Protein-coding gene on chromosome 14 (81,260,652 to 81,436,517, reverse strand). Ensembl gene ENSG00000140022.
Subcellular location: Cytoplasm; Membrane; Synapse, synaptosome
Subcellular location (Human Protein Atlas): Cytosol; Nucleoli
Pathways (Reactome):
Vesicle-mediated transport: Cargo recognition for clathrin-mediated endocytosis; Clathrin-mediated endocytosis
Gene Ontology:
Molecular function: protein binding; clathrin adaptor activity
Biological process: synaptic vesicle endocytosis; clathrin-dependent endocytosis; regulation of endocytosis; endocytosis
Cellular component: cytosol; AP-2 adaptor complex; synaptic vesicle; cytoplasm; membrane; synapse
Genetic constraint (gnomAD): Loss-of-function variants: 29 observed, 65.77 expected, observed/expected ratio (o/e) 0.44, 90% interval 0.33 to 0.6. The upper end of that interval is the gene's LOEUF score, 0.6, which puts it in group 2 of 6, group 1 being the genes least tolerant of losing a copy. Missense variants: 1,052 observed, 1,166.5 expected, observed/expected ratio (o/e) 0.9, 90% interval 0.86 to 0.95. Synonymous variants: 403 observed, 436.63 expected, observed/expected ratio (o/e) 0.92, 90% interval 0.85 to 1.
Homologues: Orthologues: macaque STON2 (98% identical), dog STON2 (91% identical), chimpanzee STON2 (91% identical), rabbit STON2 (88% identical), pig STON2 (86% identical), guinea pig STON2 (85% identical), mouse Ston2 (84% identical), rat Ston2 (83% identical), tropical clawed frog STON2 (51% identical), zebrafish ston2 (43% identical), Caenorhabditis elegans unc-41 (27% identical), Drosophila melanogaster stnB (26% identical). Paralogues in human: STON1 (27% identical), AP1M1 (10% identical), AP1M2 (10% identical), AP2M1 (10% identical), AP4M1 (8% identical), AP3M1 (8% identical), AP3M2 (7% identical).